OCLN (occludin)
Diseases named in the same sentence as OCLN in open-access papers (continued):
Sharing a sentence is not in itself a finding about the gene and the disease.
ZIKV infection (3 papers, 2019 to 2025). "ZIKV infection significantly decreased claudin-5, occludin, and ZO-1 protein levels in cells with silenced Bmal1 gene." (PMID 40313764, 2025). "The in vitro data fully corroborated with animal experiments in which we observed that ZIKV infection downregulated the expression of claudin-5, occludin, JAM-3, and ZO-1 protein levels in Bmal1ECKO mice." (PMID 40313764, 2025). "ZIKV infection resulted in a marked decrease in claudin-5, occludin, JAM-3, and ZO-1 expression levels in these mice." (PMID 40313764, 2025). "In the next series of experiments, we focused on the impact of ZIKV infection and/or Bmal1 silencing on the expression of TJ genes and proteins, such as claudin-5, occludin, zona occludens (ZO-1), and junctional adhesion molecule-3 (JAM-3)." (PMID 40313764, 2025). "The results of the western blotting assay clearly depicted a decreasing expression of ZO-1 and occludin in JEG-3 cells in the presence of ZIKV infection compared to that in the mock control group." (PMID 32153526, 2020). "Importantly, these changes were consistent with the downregulation of the expression of claudin-5, occludin, and ZO-1 proteins in endothelial cells subjected to ZIKV infections and Bmal1 silencing." (PMID 40313764, 2025). "Importantly, ZIKV infection in Bmal1ECKO mice resulted in a significant decrease in the expression of claudin-5, occludin, JAM-3, and ZO-1 proteins when compared to controls." (PMID 40313764, 2025). "Moreover, in JEG-3 cells, ZIKV infection reduces the amount of tight junction proteins, ZO-1 and occludin, through the proteasomal degradation pathway, resulting in disruption of tight junction." (PMID 32153526, 2020). "Western blot analysis showed a decrease in occludin expression in response to ZIKV infection." (PMID 31569528, 2019). "The results of RT-qPCR depicted no significant change of mRNA level of ZO-1 and occludin in both JEG-3 and hCMEC/D3 cells regardless of ZIKV infection." (PMID 32153526, 2020).
acute liver failure (2 papers, 2021 to 2025). Rapid deterioration of liver function causing encephalopathy and coagulopathy. "EGFR signaling is involved in the regulation of gene expression in endothelial cells, e.g. it has been shown that the tight junction protein occludin in brain endothelial cells of mice with acute liver failure was regulated by EGFR." (PMID 41574208, 2025). "In acute liver failure, MMP9 also degrades occludin and CLDN5 to increase vascular permeability." (PMID 33799999, 2021).
alcoholic steatohepatitis (2 papers, 2017 to 2022). "It was shown that occludin was endocytosed via macropinocytosis-like pathway as the underlying mechanism of barrier disruption in mouse model of alcoholic steatohepatitis in vivo and in vitro." (PMID 35694541, 2022). "Interestingly, decreased levels of tight junction protein Occludin and increased Claudin-2 overwhelmingly show gut leakiness more often associated with IBS, NAFLD and alcoholic steatohepatitis." (PMID 28328972, 2017).
autoimmune disease (2 papers, 2023). A disorder resulting from loss of function or tissue destruction of an organ or multiple organs, arising from humoral or cellular immune responses of the individual to their own tissue constituents. "Furthermore, we identified that significant positive linear correlations between serum occludin/zonulin antibodies and circulating autoantibodies could be used to determine autoimmune diseases." (PMID 38003542, 2023).
Autoimmunity (2 papers, 2023 to 2024). The occurrence of an immune reaction against the organism's own cells or tissues. "In this study, we investigate the relationship between zonulin/occludin antibodies, which are used to determine intestinal permeability, with autoantibodies used to diagnose autoimmunity." (PMID 38003542, 2023).
celiac disease (2 papers, 2014 to 2021). An autoimmune genetic disorder with an unknown pattern of inheritance that primarily affects the digestive tract. "Occludin is a tight junction protein crucial for maintaining intestinal barrier integrity and impairments in the intestinal epithelial barrier increase the risk of numerous disorders, including metabolic endotoxemia, inflammatory bowel and celiac diseases." (PMID 33494480, 2021). "Celiac disease is characterized by enhanced intestinal paracellular permeability due to alterations of function and expression of tight junction (TJ) proteins including ZO-1, Claudin-1 and Occludin." (PMID 24483336, 2014).
cervical cancer (2 papers, 2016 to 2021). A primary or metastatic malignant neoplasm involving the cervix. "In cervical cancer cells, occludin protein was down-regulated by E2 through proteolytic cleavage by MMP-7, leading to tight junction destabilization, further explaining the observation that TJs were disrupted during zinc deficiency." (PMID 26731262, 2016). "While previous studies have demonstrated that estrogen down-regulated occludin in cervical cancer cells, its action on liver cells was unknown." (PMID 26731262, 2016). "A previous study showed that supplementation of CA could increase expression of Occludin and claudin in TGF-β1-stimulated/unstimulated human cervical cancer cell lines (C-4I)." (PMID 34867926, 2021).
Chlamydia infection (2 papers, 2019 to 2025). "While direct evidence in Chlamydia infection is limited, DSG2 and OCLN are known to regulate epithelial tight junction integrity, and their down-regulation may compromise barrier function and increase susceptibility to infection." (PMID 41042872, 2025).
chronic hepatitis C (2 papers, 2016 to 2019). "We sought to determine if the baseline hepatic levels of miR-122, miR-29b, Claudin, Occludin, Protein Kinase R (PKR) or PKR activator (PRKRA) were correlated with HCV RNA or stage of fibrosis in patients with chronic hepatitis C (CHC)." (PMID 30957098, 2019).
co-infection (2 papers, 2020 to 2022). "In the present study, co-infection with CCP also upregulated the mRNA levels of occludin, ZO-1, and claudin-1 in the intestine." (PMID 36496951, 2022). "As representative protein components of the intra- and intercellular tight junction complex, we choose zona occludens 1 (Zo-1/Tjp1) and occludin (Ocln) and evaluated by IFA whether infection with the parasites alone or in co-infection lead to alterations in barrier integrity." (PMID 33692963, 2020).
collagenous colitis (2 papers, 2018 to 2023). A type of microscopic colitis of unknown etiology. "Occludin downregulation has been reported for CD, UC and collagenous colitis." (PMID 30728783, 2018).
COVID-19 (2 papers, 2023 to 2024). A disease caused by infection with severe acute respiratory syndrome coronavirus 2. "Tight junctions of the seminiferous tubules were also compromised in COVID-19 patients, with reduced levels of occludin and claudin-11." (PMID 36797789, 2023). "When the cells were treated with MVs derived from R patients vaccinated with the COVID-19 vaccine, the response of the cells was changed, and a significant reduction in the expression of OCLN, CLDN2, and E-CAD (p < 0.005) was induced, while the other proteins were not significantly modulated." (PMID 39201543, 2024).
deafness (2 papers, 2014 to 2025). An inherited or acquired condition characterized by the complete loss of the ability to hear from one or both ears. "Moreover, the occludin deficiency led to dislocalization of tricellulin, a gene responsible for human deafness DFNB49." (PMID 25063198, 2014). "The mutations of tricellulin were reported to cause human deafness DFNB49, and occludin was reported to support tricellular localization of tricellulin." (PMID 25063198, 2014).
diabetic cardiomyopathy (2 papers, 2021 to 2025). Diabetic cardiomyopathy is a disorder of the heart muscle in people with diabetes. "Moreover, myricetin caused an increase in occludin expression and the number of goblet cells in diabetic cardiomyopathy mice." (PMID 40362425, 2025). "The results demonstrated that ZO-1, occludin, and claudin-1 expressions were decreased in the intestinal tissues of diabetic cardiomyopathy mice." (PMID 34084135, 2021). "Compared with diabetic cardiomyopathy mice unfed with gut content, the expression of occludin, the cardiac function, and the number of goblet cells in diabetic cardiomyopathy mice fed by gut contents were higher, whereas TLR4/MyD88 pathway-related proteins and cardiomyocyte hypertrophy were reduced." (PMID 40362425, 2025). "When comparing diabetic cardiomyopathy (DCM) mice that were not fed gut content with those that were, the latter demonstrated improved cardiac function, increased goblet cells, and higher occludin expression." (PMID 40362425, 2025).
diabetic nephropathy (2 papers, 2023 to 2024). "We concluded that Azilsartan alleviated diabetic nephropathy-induced increase in Uterine artery embolization (UAE) mediated by the KLF2/occludin axis." (PMID 38462692, 2024). "In studies of diabetic nephropathy pathogenesis, it is discovered that the disruption in expression and translocation of ZO-1 and occludin in glomerular endothelial cells could be stimulated by reactive oxygen species and RhoA/ROCK pathway." (PMID 37430272, 2023).
dry eye (2 papers, 2021 to 2022). "In the dry eye model proposed, an increased secretion of IL-1β was observed, as well as an upregulation of NF-κB, occludin and galectin-3 mRNA expression." (PMID 35562958, 2022). "The confocal microscopy study of corneal epithelium revealed a decreased expression of zonula occludens-1 (ZO-1), occludin, and keratin 12 (K12) in the CEC-induced dry eye." (PMID 34750552, 2021).
ductal adenocarcinoma of the pancreas (2 papers, 2025). "In ductal adenocarcinoma of the pancreas (p = 0.005) and in high-grade serous ovarian cancer (p = 0.0133), low occludin staining was associated with advanced pT stage." (PMID 40173205, 2025).
encephalitis (2 papers, 2020 to 2023). An acute inflammatory process affecting the brain parenchyma. "IFN-γ has been shown to decrease tight junction proteins in blood vessels, such as occludin, which was associated with BBB disruption in LGI1 encephalitis." (PMID 37644514, 2023).
enteropathy (2 papers, 2018 to 2021). "During the enteropathy caused by NSAIDs, we observed alterations in the expression of critical tight junction proteins, ZO-1, CLDN-1, and OCLN." (PMID 34684313, 2021). "By contrast, in rats with diclofenac-induced enteropathy the expression of occludin was markedly reduced." (PMID 30555323, 2018). "However, the administration of rifaximin to animals with diclofenac-induced enteropathy restored the occludin expression to values similar to those detected in control animals." (PMID 30555323, 2018).
epilepsy (2 papers, 2025 to 2026). A brain disorder characterized by episodes of abnormally increased neuronal discharge resulting in transient episodes of sensory or motor neurological dysfunction, or psychic dysfunction. "Consistently, Western blotting and immunohistochemistry revealed significantly higher occludin expression in the L. eligens-treated epilepsy group compared to PBS-treated epilepsy group." (PMID 41356796, 2026). "Western blotting and immunohistochemical analyses revealed significantly reduced cortical occludin levels in the PBS-treated epilepsy group, which were restored in the L. eligens-treated group." (PMID 41356796, 2026). "As a consequence, JAM2, JAM3 (junctional adhesion molecule 2 and 3 [MIM: 606870 and 606871]), OCLN (occludin [MIM: 602876] and ESAM (endothelial cell adhesion molecule [MIM: 614281])dysfunction can present with overlapping clinical features showing severe developmental encephalopathies and epilepsy." (PMID 39414991, 2025).
esophageal squamous cell carcinoma (2 papers, 2013 to 2019). Esophageal squamous cell carcinoma (ESCC) is a type of esophageal carcinoma (EC) that can affect any part of the esophagus, but is usually located in the upper or middle third. "Low expression of occludin has been reported for the esophageal squamous cell carcinoma (ESCC) as compared to the adjacent non-neoplastic specimens." (PMID 31754355, 2019).
fibrosis (2 papers, 2022 to 2024). the formation of excess fibrous connective tissue in an organ or tissue in a reparative or reactive process. "Research has shown that the expression of Occludin in the small intestine of mice decreased significantly after the first injection of CCl4, and the bacterial translocation (CCl4, 4 times) preceded the imbalance of gut microbes (CCl4, 24 times; bridging fibrosis)." (PMID 38606180, 2024).
Hearing impairment (2 papers, 2014 to 2022). A decreased magnitude of the sensory perception of sound. "Downregulations in claudin-5 and occludin expression were associated with increased BLB permeability in the pathology of noise-induced hearing impairments, although the mechanism remains poorly understood." (PMID 35496913, 2022). "All these findings suggest that both decrease of Claudin-5 and Occludin and increased BLB permeability are involved in the pathologic process of noise-induced hearing impairment; however, the causal relationship and underlying mechanisms should be further investigated." (PMID 25539640, 2014). "All these findings suggest that Claudin-5 and Occludin are involved in the noise-induced BLB ultrastructure changes, increased BLB permeability and the hearing impairment." (PMID 25539640, 2014).
hyperandrogenemia (2 papers, 2022 to 2025). "Elevated testosterone levels in women with the endocrine disorder polycystic ovary syndrome (PCOS) influence the integrity of tight junctions in the endometrial epithelium by decreasing Cldn4 and occludin." (PMID 40867502, 2025).
internal carotid artery stenosis (2 papers, 2020 to 2022). Carotid stenosis is a narrowing or constriction of the inner surface (lumen) of the carotid artery, usually caused by atherosclerosis. "The authors’ research has shown a significant increase in MMP2 and MMP9 activity and a significant increase in the concentrations of claudin-1 and occludin in the blood of patients undergoing the reconstruction of internal carotid artery stenosis." (PMID 35627746, 2022).
intracerebral hemorrhage (2 papers, 2018 to 2024). A cerebrovascular disorder characterized by bleeding into one or both cerebral hemispheres including the basal ganglia and the cerebral cortex. "In intracerebral hemorrhage mouse models, the normalization of tight junction proteins ZO-1 and occludin by fibroblasts has been observed to enhance BBB integrity." (PMID 39030617, 2024). "The results are in agreement with those of Zhao and coworkers, who have shown that administration of the selective P2X7R inhibitor A438079 upregulates the expression of occludin in rats subjected to experimental intracerebral hemorrhage." (PMID 30091000, 2018).
lupus (2 papers, 2022 to 2025). "Total claudin-1, occludin, and ZO-1 expression was significantly upregulated in the lupus mice and restored in the CLC group." (PMID 40507090, 2025). "In addition, the expression of the blood–brain barrier endothelial cell tight junction proteins claudin-1, occludin, and ZO-1 was abnormally modified in lupus mice and was restored in the CLC group." (PMID 40507090, 2025). "Furthermore, the expression of Tyr-phosphorylated forms of claudin-1, occludin, and ZO-1 was increased in the lupus mice." (PMID 40507090, 2025).
malaria (2 papers, 2009 to 2018). Malaria is a serious and sometimes fatal disease caused by a parasite that commonly infects a certain type of mosquito which feeds on humans. "Quantitative PCR of human umbilical vascular endothelial cells (HUVECs) cultured with P. falciparum samples from patients with uncomplicated malaria showed increased mRNA levels of occludin, vinculin, and ZO-1." (PMID 19680452, 2009). "It would be interesting to assess the disruption of junctional molecules, which are complexed in TJ and AJ, i.e. occludin, claudins, junctional adhesion molecule (JAM), VE-cadherin, β-catenin, and the cytoskeleton changes in ECs exposed to malaria parasites/sera." (PMID 30026484, 2018).
memory impairment (2 papers, 2022 to 2025). "Cumulatively, the results of these behavioral tests indicate that the loss of N-cadherin and, consequently, occludin TJs, may be a contributing factor to memory impairment." (PMID 40503940, 2025).
multiple myeloma (2 papers, 2020 to 2022). "Apart from CLDN, ZO-1 overexpression is also reported to be involved in TAZ/TEAD activation in multiple myeloma, and occludin and YAP/TEAD was reported to bind in pancreatic ductal epithelium and pancreatic cancer." (PMID 32481659, 2020). "In agreement with the gene model, compared with bortezomib-sensitive myeloma cell lines (negative control), there was an increase in mRNA expression of SCN9A, RGS7, NTF3, HSPB8, and ZBED1 and a decrease in CCND1, COBLL1, EGR1, OCLN, and ZBED1 mRNA expression of bortezomib-resistant cell lines." (PMID 36467498, 2022).
nasal polyps (2 papers, 2017 to 2023). "We showed that epithelial TJs, mainly represented by occludin and ZO-1, which are crucial proteins in producing the rate-limiting barrier to inhaled pathogens, are decreased in nasal polyps." (PMID 37047067, 2023). "OSM and IL-6 were both overexpressed, and TJ (ZO-1 and occludin) expression was decreased in the nasal polyps compared to the control mucosa." (PMID 37047067, 2023). "We reported a decrease in the expression of occludin (p = 0.0159) and ZO-1 (p = 0.0079) in nasal polyps when compared to non-inflammatory nasal mucosa." (PMID 37047067, 2023).
oral squamous cell carcinoma (2 papers, 2016 to 2025). "No study, to the best of our knowledge shows the association of claudin-5, claudin-7 together with occludin expression in oral squamous cell carcinoma (OSCC) and their clinic-pathological prognostic factors." (PMID 27398181, 2016). "The objective of this study was to investigate the expression of claudin-5, claudin-7 and occludin in oral squamous cell carcinoma (OSCC) and their relationships with the prognostically-related clinico-pathologic features." (PMID 27398181, 2016). "Key words:Claudin, occludin, oral squamous cell carcinoma, tight junctions, oral cancer." (PMID 27398181, 2016).
orchitis (2 papers, 2016 to 2023). Inflammation of one or both testes due to viral or bacterial infections. "In a model of orchitis induced by LPS in bovine Sertoli cells, LPS induced IL-6 and IL-1 β, and downregulated the expression of ZO-1 and occludin, resulting in the inflammatory response of Sertoli cells and TJ damage." (PMID 37376572, 2023). "Furthermore, we uncovered the relationship between MKP-1 and occludin by LPS stimuli, and our study provided a novel mechanism between local immunosuppressive molecules and Sertoli cell junction dynamics during LPS-induced acute testis inflammation." (PMID 27783995, 2016).
pneumococcal infection (2 papers, 2024 to 2025). Infections with bacteria of the species streptococcus pneumoniae. "Semi-automated analysis of junction images also demonstrated a loss of ZO-1 and occludin continuity during pneumococcal infection." (PMID 41042679, 2025).
sleep disorder (2 papers, 2022 to 2025). A change from the patient's baseline sleeping pattern, in the hours slept and/or an alteration/dysfunction in the stages of sleep. "OCLN maintains blood–brain barrier integrity, with implications for neuroinflammation and sleep disorders." (PMID 41226651, 2025). "To verify the influence of light/dark phase shift on intestinal barrier function, we detected the fluorescence expression of ZO-1 and occludin in the colonic tissue of normal controls and patients with sleep disorders." (PMID 36177467, 2022). "Results showed that the fluorescence intensity of ZO-1 and occludin was significantly weakened in sleep disorder patients compared to the control group." (PMID 36177467, 2022). "Besides, we confirmed that the fluorescence intensity of ZO-1 and occludin was significantly weakened in patients with sleep disorders compared to normal controls." (PMID 36177467, 2022).